MMP9 (matrix metallopeptidase 9)
Diseases named in the same sentence as MMP9 in open-access papers (continued):
Sharing a sentence is not in itself a finding about the gene and the disease.
tumor (continued). "In contrast, MMP-9-targeted nanomedicines employ active targeting, binding to overexpressed MMP-9 in the tumor microenvironment." (PMID 40284474, 2025). "Beyond the vasculature, valsartan has been shown to inhibit MMP-9-dependent migration and invasion in tumor and fibrotic contexts." (PMID 41304763, 2025). "In the tumor microenvironment, MMP9 degrades type I collagen, releasing fragments that engage the inhibitory receptor leukocyte-associated immunoglobulin-like receptor-1 (Lair-1) on T cells and attenuate TCR signaling." (PMID 41306770, 2025). "SFN also impacts the tumour microenvironment, particularly through its anti-angiogenic properties and inhibition of matrix metalloproteinases (MMPs), such as MMP-9." (PMID 40426874, 2025). "Although numerous in vitro studies have demonstrated the inhibitory effects of wine-derived compounds on MMP-2 and MMP-9 expression in tumor cells, translating these findings into in vivo contexts remains challenging." (PMID 40563423, 2025). "According to the current research, Pic downregulates the activity of NF-κB and enhances anti-tumor properties by suppressing the expression of MMP-9 in HPC cells." (PMID 40563423, 2025). "As a result of this acidic environment, increased expression and activation of pH‐sensitive metastasis‐promoting proteins such as MMP‐2 and MMP‐9 occur and significantly promote the invasive potential of tumor cells." (PMID 40150879, 2025). "Among these genes, we found MMP9 (Matrix Metallopeptidase 9), which is involved in the degradation of the extracellular matrix, facilitating tumor invasion and metastasis." (PMID 41402347, 2025). "MMP‐9 also has a dual role in the activation of TGF‐β at the tumor‐bone interface in osteolytic lesions." (PMID 40304052, 2025). "Tumor-associated neutrophils infiltrate tumor sites, where they secrete elevated levels of VEGF-A and MMP9, thereby driving tumor LYM and lymph node metastasis." (PMID 41262238, 2025). "The increase in neutrophil numbers leads to an increase in matrix metalloproteinase-9 (MMP-9) levels, which appears to contribute to angiogenesis and tumor progression, leading to a poor prognosis." (PMID 41516032, 2025). "MMP2 and MMP9 produced by tumor cells are controlled by adipocyte-derived leptin and IL6 by activating FAK- and SRC-dependent pathways." (PMID 40841364, 2025). "Given MMP-9’s crucial role in tumor progression—driving EMT, angiogenesis, growth, and metastasis—and its involvement in the pathogenesis of vascular diseases, the development of MMP-9-related nanomedicines represents a promising therapeutic avenue." (PMID 40284474, 2025). "Significantly, Western blot tests demonstrated decreased levels of MMP2 and MMP9, pivotal elements in the spread of cancer, as they aid in breaking down the extracellular matrix and facilitating tumor metastasis." (PMID 38415456, 2025). "The coinjection of tumor cells with tumor-derived MDSCs enhances tumor angiogenesis, as MDSCs produce MMP9, which regulates the bioavailability of vascular endothelial growth factor (VEGF) and promotes angiogenesis." (PMID 41368628, 2025). "Mechanistically, loss of Klk1 promoted extracellular matrix (ECM) remodeling by upregulating Mmp2, Mmp9, Fap, decorin, and β‐catenin, thereby promoting epithelial‐mesenchymal transition and tumor progression." (PMID 40859429, 2025). "A positive correlation was observed between SP abundance and MMP-9 expression (all p < 0.05) across tumor stages." (PMID 40321254, 2025). "Protumor neutrophils can release MMP-9, which promotes angiogenesis and tumor cell proliferation and can suppress NK cells function." (PMID 40391215, 2025). "By enhancing MMP-9 expression, TAMs are associated with elevated VEGF-A levels, inducing tumor growth and tumor angiogenesis in HCC, mediated by the type 1 insulin-like growth factor (IGF-1) signaling pathway through the PI3-K and MAPK pathways." (PMID 39796695, 2024).
tumor (continued). "Several proteases, such as MMP-2, MMP-9, or matriptase, have been described to accumulate in the tumor microenvironment." (PMID 38804305, 2024). "Removal of the mask via MMP-9 protease cleavage, a protease that is frequently overexpressed in the tumor microenvironment (TME), led to complete regeneration of binding and cytosol-penetrating capabilities." (PMID 38804305, 2024). "MMP-9 originating from inflammatory cells contributes to the occurrence and progression of tumors, along with tumor angiogenesis." (PMID 39582871, 2024). "A subsequent analysis of other related factors further indicated that the patients with decreased MMP-9 levels at the 2nd had higher disease control rates, tumor shrinkage, longer PFS, and overall survival than those with increased changes." (PMID 39199626, 2024). "Increased expression of MMP-9 was detected around the tumor capsule in HCC and was strongly correlated with tumor size, capsule status, tumor stage, and HCC recurrence risk." (PMID 38362156, 2024). "Mechanistically, macrophage-derived MMP-9 activates the PI3K/AKT pathway in tumor cells leading to the upregulation of SNAIL and subsequent EMT." (PMID 39555068, 2024). "Gene expressions for tumor promoting genes such as Arg1, Il6, Il10, Mmp9, Lgals9, and Vegfa were significantly decreased, whereas that of the tumor suppressive gene such as Il12 increased." (PMID 39702544, 2024). "Degradation of stromal collagen by MMP-2 and MMP-9 is the biochemical basis for tumor cell migration and invasion into surrounding tissues." (PMID 38776295, 2024). "The fact that MMP-9 immunoexpression is observed in the infiltrative tumour border configuration supports the thesis that such proteolytic activity promotes the aggressive potential of cancer cells." (PMID 39337393, 2024). "Both studies that examined tumour MMP9 demonstrated a lower OS with >50% tumour cell staining for MMP9." (PMID 38398089, 2024). "RT‐qPCR analysis of tumor specimens revealed elevated mRNA expression levels of TNFα and MMP9 in BIPA." (PMID 38739004, 2024). "The MMP9 was mainly expressed in tumor tissue and less expressed in surrounding tissue; some of those have higher and variable expressions due to inter-individual variability." (PMID 39132498, 2024). "On the one hand, they contribute to tumor promotion by secreting matrix metalloproteinase-9(MMP-9) and vascular endothelial growth factor(VEGF)." (PMID 39680287, 2024). "Higher levels of MMP9 have been correlated with higher tumor grades and resistance to endocrine therapy." (PMID 39057065, 2024). "The presence of CAFs in tumor cells, which secrete LH in conjunction with MMP-9, significantly enhances the likelihood of collagen fiber degradation and further fosters cross-linking in the milieu of TGF-β." (PMID 39680287, 2024). "The MAPK pathway and MMP9 expression were significantly inhibited in the tumor tissues of TNBC patients treated with atorvastatin." (PMID 38907234, 2024). "This is corroborated by the findings indicating elevated MMP‐9 expression in circulating tumour cells, lung and adrenal gland metastasis tumours, and its correlation with a worse overall survival rate." (PMID 38506084, 2024). "Increased levels of IL-6 and C-reactive protein (CRP) alongside MMP9 with advancing CRC stages indicate the role of systemic inflammation in modulating the tumor microenvironment and driving cancer progression." (PMID 39664453, 2024). "VEGF/VEGFR2 signaling promotes metastatic spread to secondary organs by inducing vessel permeability, facilitating invasion of tumor cells into metastatic tissues through augmenting expression of MMPs such as MMP9 that degrade the ECM." (PMID 38441970, 2024). "MMP9 facilitates the release of VEGF (vascular endothelial growth factor) that is sequestered in the tumor extracellular environment." (PMID 39796646, 2024).
tumor (continued). "The majority of M2 subtypes are anti-inflammatory and pro-angiogenic, secreting growth factors (VEGF, PDGF) and matrix metalloproteinases (MMP2, MMP9) which boost tumor growth, metastasis, and invasion." (PMID 38935134, 2024). "Western blot analysis of tumor specimens revealed higher protein expression levels of TNFα, phosphorylated p38 (p‐p38), and MMP9 in the TNFα overexpression group." (PMID 38739004, 2024). "B cells enhance EC function in a STAT3-dependent manner by expressing VEGFA, FGF2, and MMP-9, thereby promoting tumor angiogenesis." (PMID 39691707, 2024). "Next, we performed western blotting assay to measure the expression levels of key protein markers associated with tumor progression, including PCNA, MMP9, and cleaved caspase-3." (PMID 38760791, 2024). "Blockade of proMMP-2 activation, reduction in MMP-9 expression, reduction in endothelial cell invasion, inhibition of tumor progression, reduction in metastasis rate and angiogenesis." (PMID 39594665, 2024). "Matrix metalloproteinases, such as MMP-2 and MMP-9, are considered potential putative markers for tumor diagnosis in clinical validation due to their easy detection in body fluids." (PMID 38774755, 2024). "The expression of HOTAIR leads to the upregulation of matrix metalloproteinase-9 (MMP-9), vascular endothelial growth factor (VEGF), and genes associated with the epithelial–mesenchymal transition (EMT), thereby promoting tumor aggressiveness in CC." (PMID 38434620, 2024). "MMPs such as the gelatinases MMP-2 and MMP-9 have a particular contribution to cancer invasion and metastases, with their overexpression being reported in numerous neoplasms, including CRC." (PMID 38792627, 2024). "can confer cancer cells with enhanced tumor invasion and metastatic capabilities by promoting matrix metalloproteinase 9 (MMP9), an extracellular matrix degrader, through activation of protease-activated receptor 2 (PAR2) and the ERK1/2-Ets1/3-p38 pathway." (PMID 38807771, 2024). "In this study, we presented a single-cell atlas of advanced HCC, revealing distinct expression patterns of MICA and MMP9 in tumor cells and macrophages, respectively." (PMID 38254761, 2024). "Since ECM remodeling promotes the migration and invasion of tumor cells, the activity of MMP-9 and MMP-2 was employed as molecular biomarkers supporting the invasion and migration assay results." (PMID 39309445, 2024). "MMP9-positive macrophages have been shown to play crucial roles in tumor tissue remodeling, monocyte migration, tumor cell migration and metastasis, as well as tumor immune evasion and response to immunotherapy." (PMID 38254761, 2024). "RAGE/S100A7 interactions conditions the tumor microenvironment by increasing the recruitment of MMP9-positive TAMs." (PMID 39830522, 2024). "At the same time, peritumoral stromal neutrophils in turn promote invasive margin angiogenesis by up-regulating MMP9 expression and ultimately promote tumor progression." (PMID 39906741, 2024). "TANs can secrete MMP9, which facilitates angiogenesis and tumor invasion and supports cancer foci to expand." (PMID 39338413, 2024). "Inhibiting ICAM1 significantly suppressed MAPK pathway activation, decreased MMP9 expression, and resulted in notable tumor shrinkage." (PMID 38907234, 2024). "MMP2 and MMP9 play a crucial role in tumor cell invasion and metastasis by degrading the basal membrane." (PMID 39343952, 2024). "The genes CDH1, CDH2, and MMP9, which are involved in promoting tumour cell metastasis, was significantly increased in H128-LM cells and H128-BPM cells compared to H128 cells." (PMID 38644473, 2024). "In contrast, N2 neutrophils support tumor expansion by expressing arginase, matrix metalloproteinase-9 (MMP-9), VEGF, and chemokines such as CCL2, CCL5, and CXCL4." (PMID 39795864, 2024). "Protein expression levels of SPHK2, metal matrix protease 2 (MMP2), MMP9 and urokinase-type plasminogen activator (uPA) in tumor tissues were assessed by immunohistochemistry (IHC)." (PMID 38965120, 2024).
tumor (continued). "In ccRCC, an increasing number of studies have shown that MMP9 promotes tumor invasion and migration." (PMID 38375034, 2024). "Chronic stress activates cAMP/PKA signaling pathway through adrenergic receptor ADRB2, leading to increased expression of VEGF, MMP2 and MMP9 to promote angiogenesis and tumor growth." (PMID 39054537, 2024). "TNF-α also induces MMP-9 expression which enhances tumor cells’ ability to migrate and invade other tissues." (PMID 38935134, 2024). "Reduced MMP-2 and MMP-9 expression was noted in the tumor tissue, inhibiting the invasion and metastasis of neoplastic cells." (PMID 39335164, 2024). "It exerts its anti-tumor effects by down-regulating the expression of Vimentin and MMP-9 and up-regulating the expression of E-cadherin." (PMID 39193331, 2024). "There are many extensive studies revealed that MMP9 promoted tumor progression via modulating the TME." (PMID 38577608, 2024). "In prostate carcinoma cells, inhibiting NF-κB activity resulted in the downregulation of MMP-9 mRNA, leading to decreased invasion of tumor." (PMID 39493763, 2024). "Neutrophils inside the tumor tissue, particularly those generating IL-17, via secreting matrix metalloprotein 9 (MMP-9) promote angiogenesis and tumor progression." (PMID 39676857, 2024). "The 5-marker panel (MMP9, tumor volume, presence of brainstem compression, CSF cleft, and cystic change) exhibited the best performance (AUC5-marker = 0.95, Sensitivity 80%, Specificity 100%)." (PMID 38887507, 2024). "In endometrial cancer, adiponectin activates AMPK and downregulates Bcl-2 and MMP-9 expression, consequently inhibiting the invasion of tumor cells and promoting tumor cell apoptosis." (PMID 38800384, 2024). "Inhibition of FOXM1 has been shown to reduce the expression of MMP-2 and MMP-9, and suppress the migration and invasion of tumor cells." (PMID 39594778, 2024). "All the evaluated markers, except for MMP9/13, were more abundant in the tumor parenchyma than in the tumor stroma." (PMID 38858774, 2024). "Animal studies indicated that serpin E2 is unnecessary for breast tumor growth, but essential for tumor metastasis, and MMP9 is a key mediator of serpin E2-mediated tumor metastasis." (PMID 38469181, 2024). "The short peptide sequence PLGLAG is an MMP2/MMP9-sensitive linker fragment that breaks in tumor tissue." (PMID 38399294, 2024). "First, neutrophils are known to produce immunosuppressive factors and angiogenic molecules such as reactive oxygen species, vascular endothelial growth factor (VEGF), and matrix metalloproteinase 9 (MMP-9), which can promote tumor growth." (PMID 39544301, 2024). "The expression of MMP-9 disrupts the extracellular matrix and transcribes integrins to promote the targeted movement of breast tumor cells, eventually inducing tumor invasion and metastasis." (PMID 38236337, 2024). "To investigate the interplay between MICA+ tumor cells and MMP9+ macrophages, we employed CellChat, a computational tool, to unravel the intricate cell-cell communication and predict significant biological insights from scRNA-seq data." (PMID 38254761, 2024). "Matrix metalloproteinase 9 (MMP9), responsible for extracellular matrix degradation facilitating tumor invasion and metastasis, was also downregulated in the K-OVV group." (PMID 39519023, 2024). "Tumor-associated neutrophils secrete a plethora of pro-angiogenic molecules including VEGF, FGF-2, Bv8, IL-17, and MMP-9." (PMID 38580870, 2024). "The p38 pathway has a unique role in modulating MMP9 expression, differing from the tumor-suppressive effects attributed to its other isoforms." (PMID 39664453, 2024). "MMP-2 and MMP-9 play vital roles in tumor invasion due to their potent ability to degrade collagen type IV." (PMID 38827318, 2024). "Upon reaching the tumor site, MMP-9 cleaved the substrate peptide, triggering the stimuli-responsive release of DNase I from mP-NPs-DNase/PTX." (PMID 39143953, 2024).
tumor (continued). "Western blot analysis revealed that melittin significantly reduced the expression levels of MMP2 and MMP9 in a dose-dependent manner, indicating impaired tumor cell movement, consistent with the results from wound-healing and transwell assays." (PMID 39519238, 2024). "This activation leads to the polarization of macrophages towards the M2 type, increased expression, and secretion of MMP2 and MMP9, thereby reshaping the extracellular matrix and facilitating tumor cell invasion and metastasis." (PMID 39695147, 2024). "We identified the existence of an interaction between MICA+ tumor cells and MMP9+ macrophages mediated via the PROS1-AXL axis." (PMID 38254761, 2024). "There was a moderate increase in perivascular MMP9 in large compared to small VS (average tumor diameter 3.9 vs 1.1 cm, P = .0019), and a significant increase in parenchymal MMP9 in large tumors (P < .0001)." (PMID 38887507, 2024). "By activating NF-κB, it can induce MMP production in tumor cells, especially MMP-9, leading to the invasion and dissemination of tumor cells." (PMID 39061247, 2024). "Arg1 17 and Ym1 18 are fundamental features of M2 macrophages, with the secretion of Arg1 19, Ym1 20, MMP2 21 and MMP9 22 by macrophages promoting the metastasis of tumor cells." (PMID 38356723, 2024). "Considering that EMT is crucial for initiating the process of tumor metastasis cascade, vimentin and MMP9 have garnered significant attention as essential markers for EMT." (PMID 38388902, 2024). "Additional pre-clinical research investigating systemic knockout models of MMP-9 witnessed secondary effects of poorer immune response leading to increased overall tumor invasiveness." (PMID 38361931, 2024). "In contrast, certain tumor neutrophils have the ability to secrete matrix metalloproteinase 9 (MMP9), thereby facilitating the angiogenesis and spread of tumor cells." (PMID 39334819, 2024). "During tumor progression, MMP-9 facilitates the invasion of tumor cells into the basement membrane by degrading specific substrates such as gelatin, elastin, and collagens, thereby promoting tumor metastasis and dissemination." (PMID 39188682, 2024). "MMP-9 enhances tumor cell metastatic capacity by degrading collagen proteins of the ECM after activation by extracellular proteases." (PMID 39063556, 2024). "Migration/invasion of many tumor cells is stimulated by MMP-9, which becomes activated by proteolytic cleavage of its externalized precursor, pro-MMP-9." (PMID 38891885, 2024). "MMP‐9 previously was identified to act crucial character in tumour invasion, metastasis and angiogenesis." (PMID 38506084, 2024). "Emerging evidence underscores the role of MDSCs in tumor infiltration and promotion of angiogenesis, primarily through the secretion of matrix metallopeptidase 9 (MMP9) and their direct integration into the tumor endothelium, facilitating vasculogenesis." (PMID 39493763, 2024). "The activities of MMP-2 and MMP-9 increased by 60% and 84%, respectively, and were much higher in tumor than in control brain tissue (p < 0.0001)." (PMID 38275897, 2024). "The treatment effectively inhibited the expression of MMP-2 and MMP-9 in tumor tissue, assessed by immunohistochemical staining, and significantly decreased the tumor volume, indicating that EGCG has strong anti-cancer activity in vivo." (PMID 39335164, 2024). "Expression of MMP-9 in tumor tissue was significantly upregulated (increased of 242%, p = 0.0107) as opposed to the almost identical expression of MMP-2 (p = 0.9245;)." (PMID 38275897, 2024). "This integrative role of MMP9 connects upstream signals to facilitate tumor invasion, metastasis, and angiogenesis, pointing to its potential as a target for therapeutic interventions aimed at disrupting its pro-tumorigenic functions." (PMID 39664453, 2024). "For example, Rethnam and the colleagues reported the pro- and tumor-suppressive effects of MSCs via reducing the level of MM-derived matrix metalloproteinase-9 (MMP-9)." (PMID 38539153, 2024).